BRCA1 (BRCA1 DNA repair associated)
Diseases named in the same sentence as BRCA1 in open-access papers (continued):
Sharing a sentence is not in itself a finding about the gene and the disease.
breast cancer (continued). "Further supporting the clinical relevance of our findings, acetaldehyde treatment specifically inhibited growth of BRCA2‐deficient human tumors in xenograft models and PARP inhibitor‐resistant BRCA1‐deficient allografted mammary tumors." (PMID 28729482, 2017). "Breast cancer, of which heredity explains approximately 10–15% of the cases, with only 5% can be clarified by known genetic polymorphisms such as BRCA1 and BRCA2." (PMID 28074086, 2017). "Known genetic factors contributing to a higher lifetime risk of breast cancer comprise rare variants in BRCA1, BRCA2, PALB2, ATM and CHEK2." (PMID 28199975, 2017). "Mutations in the tumour suppressor gene breast cancer 1 (BRCA1) accounts for almost 50% hereditary breast cancer and reduced BRCA1 expression strongly correlated with accelerate growth and progression of sporadic breast cancer." (PMID 29291027, 2017). "In conclusion, this is the first study to describe VDR, RXR and PPARγ in BRCA1 mutated breast cancer." (PMID 28427429, 2017). "In a previous association study, the BRCA mutations were found in about 20% of all hereditary breast cancers and women carrying BRCA1 and BRCA2 mutation were easily caught up with breast cancer." (PMID 28982360, 2017). "Mutations in the breast cancer genes BRCA1 and BRCA2 increase the risks to breast cancer, and BRCA1 and BRCA2 proteins act as tumor suppressor genes." (PMID 28938549, 2017). "Most known cancer syndromes were first found to be associated with an increased risk of one tumor type such as breast cancer (BRCA1 and BRCA2) or colorectal cancer (APC and the DNA mismatch repair genes)." (PMID 29299148, 2017). "Little is known about the contribution of BRCA1/2 mutations to hereditary breast cancer in Colombia." (PMID 28680148, 2017). "Approximately 25% of hereditary breast cancer cases are associated with a strong familial history which can be explained by mutations in BRCA1 or BRCA2 and other lower penetrance genes." (PMID 29108258, 2017). "This beneficial effect is lost upon addition of ligand, suggesting unliganded GR displacement from BRCA1 promoter in response to steroids decreases BRCA1 expression and increases the risk for breast cancer." (PMID 28220107, 2017). "Twenty-four (30%) of 80 patients with BRCA1 mutations had been previously diagnosed and treated for breast cancer." (PMID 28182133, 2017). "The crucial role of the breast cancer susceptibility proteins, BRCA1 and BRCA2 in the DNA repair has been known since 1995." (PMID 28055979, 2017). "The overall prevalence of BRCA1/2 mutations was 50% in multiple case breast cancer families and 33% in breast and ovarian cancer families." (PMID 28680148, 2017). "Considering the higher radiosensitivity of their breast tissue and the high sensitivity of MRI for breast cancer, mammography can be avoided at least up to 35 years of age, in particular in BRCA1 mutation carriers." (PMID 28540564, 2017). "Thirteen early-stage breast cancer patients with germline mutations in either BRCA1 or BRCA2 were treated for 2 months with talazoparib." (PMID 28454587, 2017). "Since the frequent lack of hormone receptors (ER/PR) or Her2 extensively narrows the application of (anti-) endocrine therapies, BRCA1 associated breast cancers require a specially tailored therapeutic regimen." (PMID 28427429, 2017). "Annual surveillance with breast MRI has been shown to reduce incidence of advanced-stage breast cancer in women with pathogenic BRCA1/2 mutations." (PMID 28522877, 2017). "When the three groups were considered separately, the average age at diagnosis of breast cancer in the family, in the BRCA1-pathogenic, BRCA1-VUS and BRCA1-WT groups were respectively 44.1; 41.2 and 42.5 years (SD = 5.7, 9.7 and 10.7 years, respectively)." (PMID 27926510, 2017).
breast cancer (continued). "The average cumulative risk of breast cancer in female carriers above 70 years is estimated to be 57–65 and 45–49% for BRCA1 and BRCA2 mutation carriers, respectively." (PMID 28205045, 2017). "Mutation screening of the breast cancer genes BRCA1 and BRCA2 identifies a large fraction of variants of uncertain clinical significance (VUS) whose functional and clinical interpretations pose a challenge for genomic medicine." (PMID 28339459, 2017). "The strongest association with breast cancer risk among BRCA1 carriers was observed for rs6589007, located at 11q22.3 in intron 15 of the NPAT gene (p = 4.6 × 10−3) at approximately 54 kb upstream of the ATM gene." (PMID 27796716, 2017). "Unaffected women who carry BRCA1 or BRCA2 mutations face difficult choices about reducing their breast cancer risk." (PMID 28624978, 2017). "In contrast, the BRCA1 carriers at the 90th percentile of the PRS had a 39% breast cancer risk by age 50 years and 75% by age 80 years." (PMID 28376175, 2017). "The familial breast tumor samples used for defining the BRCAness profile inherit a copy of defective BRCA1/2 gene, predispose them to breast cancer when the function of the other allele is lost (again, this can be caused by different genomic mechanisms)." (PMID 29146938, 2017). "BRCA-1 (breast cancer susceptibility gene) is considered to be the cause of 5–10% of breast cancer that is transferred from either father or mother to the next generation." (PMID 28969709, 2017). "We detected several expected variants on known breast cancer-predisposing genes like BRCA1 and BRCA2, which are a confirmation of the validity of this study." (PMID 28569218, 2017). "Use of cells completely lacking endogenous BRCA1 would facilitate experiments correlating this effect of BRCA1 with its disease-causing mutations, thus linking our observations with critical aspects of pathogenesis of breast cancer in BRCA1 mutation carriers." (PMID 28270739, 2017). "We identified a region on 11q22.3 that is significantly associated with breast cancer risk in BRCA1 mutation carriers (most significant SNP rs228595 p = 7 × 10−6)." (PMID 27796716, 2017). "Cumulative lifetime breast cancer risks for male BRCA1 and BRCA2 pathogenic variant carriers are 1–2 and 5–10%, respectively." (PMID 28008555, 2017). "Specifically, for rs8170, the A allele was positively associated with breast cancer in the previous study (OR = 1.28 among BRCA1 carriers) and our study (OR = 1.08)." (PMID 28362817, 2017). "For instance, IBIS (Cuzick-Tyrer) mainly estimates the risk of breast cancer over time; furthermore, readouts of inheriting a mutant BRCA-1/2 are there." (PMID 28962650, 2017). "We evaluated associations for a total of 9,530,887 SNPs in 1,802 male carriers of BRCA1/2 mutations, including 277 patients with breast cancer, 212 patients with prostate cancer, and 1,313 controls." (PMID 28448241, 2017). "Recently a panel of BRCA1 and BRCA2, HISPANEL has been constructed with diverse mutations from Hispanic breast cancer women from USA, based on the information in manuscripts describing mutations in BRCA1 and BRCA2 from Latin American countries and data bases." (PMID 29088781, 2017). "Longer term quantitative studies are also needed to provide information about breast cancer risk to women with a BRCA1/BRCA2 mutation who are disease-free more than five years after treatment for ovarian cancer." (PMID 28780755, 2017). "Genetic and epigenetic alterations such as BRCA1/2 mutations have also been shown to affect the risk of lifetime breast cancer whereby the risks increase to 65–81% for those with BRCA1 mutation carriers and 45–85% for BRCA2 mutation carriers." (PMID 28538673, 2017).
breast cancer (continued). "Retrospective studies, suggest an estimated cumulative risk of breast cancer to 70 years of age of 40–87% for BRCA1 carriers and 27–84% for BRCA2 carriers." (PMID 28985766, 2017). "The breast cancer susceptibility proteins BRCA1 and BRCA2 have emerged as key stabilizing factors for the maintenance of replication fork integrity following replication stress." (PMID 29038425, 2017). "BRCA1 carriers at the 10th percentile of the PRS had a risk of 21% of developing breast cancer by age 50 years and a 56% risk by age 80 years." (PMID 28376175, 2017). "The low-penetrance MTHFR 677 C>T mutation has previously been linked to the luminal subtype of breast cancer, in a similar way that BRCA1 mutations predominate in patients with hormone receptor-negative breast cancer of the basal-type." (PMID 28241424, 2017). "We used the updated ER-negative PRS to predict breast cancer risk for BRCA1 carriers and the updated overall breast cancer PRS to predict breast cancer risk for BRCA2 carriers." (PMID 28376175, 2017). "Our findings, on protein and mRNA levels, strongly indicate that Nestin is associated with BRCA1 related breast cancer, the basal-like phenotype, high-grade tumour features and reduced survival with independent significance." (PMID 28439082, 2017). "In this study, we assessed the preferences for breast cancer risk-reduction treatments among women with germline BRCA1 and/or BRCA2 mutations." (PMID 28624978, 2017). "We observed a higher proportion of breast cancer cases younger than 50 years in families with pathogenic mutations in BRCA1, while most patients the BRCA1-VUS and BRCA1-WT groups reported only one or two cases diagnosed before the age of 50 (p = 0.005)." (PMID 27926510, 2017). "Breast cancer risk management in BRCA1/BRCA2 carriers with advanced ovarian cancer is an under-explored area of genetic counseling research." (PMID 28780755, 2017). "Women with BRCA1/2 mutations are willing to accept a risk of side effects in order to achieve a 90% reduction in breast cancer risk." (PMID 28624978, 2017). "The transcriptional level of BRCA1 was also tested for possible associations with pathological and morphological characteristics of breast cancer, as well as clinical characteristics, prognosis and family history." (PMID 27926510, 2017). "Many genes involved in DNA repair and cell cycle have been linked with breast cancer, including the genes BRCA1 and BRCA2 which direct DNA double-stranded break by homologous recombination." (PMID 29291027, 2017). "A recent study in an unselected breast cancer cohort reported somatic-only BRCA1/2 mutations to be present in 3% of patients, with approximately one-third (9/29) of BRCA mutations to be of somatic origin." (PMID 28525389, 2017). "Seventeen relatives of BRCA1/2 mutation carriers were diagnosed with primary breast cancer, four with primary ovarian cancer, two with melanoma and three with cervical neoplasms." (PMID 28680148, 2017). "We recently used naïve HME (BRCA1-expressing) cells infected with RasV12 (positive control) or inducible IRIS alleles to generate orthotopic mammary tumors in SCID mice." (PMID 28052035, 2017). "Given the high rate of novel variants identified in BRCA1/2 and other breast cancer-associated genes, the clinical usefulness of the data is currently limited." (PMID 28202063, 2017). "Here, we explored the efficacy and safety of ID cisplatin treatment as an alternative prophylactic therapy in the prevention of BRCA1-associated breast cancer formation, in combination with PARP-inhibition." (PMID 28977823, 2017). "Risk-reducing saplingo-oophorectomy (RRSO) offers reduction in the risk of ovarian cancer of approximately 80%, among BRCA1 and 2 carriers, and of 50% for breast cancer." (PMID 28320467, 2017). "BRCA1 andBRCA2 (breast cancer 1 and 2) are two of the best-known cancer susceptibility genes, and mutations in these genes are causally connected to the rare genetic disorder Fanconi anaemia." (PMID 29387807, 2017).
breast cancer (continued). "It has been shown to be associated with a lower risk of ovarian cancer, a lower risk of breast cancer, lower all-cause mortality, breast cancer-specific mortality, and ovarian cancer-specific mortality in BRCA1/2 mutation carriers." (PMID 28936272, 2017). "The ER-negative PRS showed a weaker association with breast cancer risk for male carriers of BRCA1/2 mutations." (PMID 28448241, 2017). "Many variants of BRCA1 or BRCA 2 have been detected in patients with breast cancer, but their related l significance is still unclear." (PMID 28881705, 2017). "The PRS for ER-negative breast cancer displayed the strongest association with breast cancer risk in BRCA1 carriers (per standard deviation HR = 1.27, 95% confidence interval [CI] = 1.23 to 1.31, P = 8.2×10−53)." (PMID 28376175, 2017). "Using this approach, we found evidence of association for a region at 11q22.3, with breast cancer risk in BRCA1 mutation carriers." (PMID 27796716, 2017). "A recent study had identified an association between an ATM haplotype and breast cancer risk in BRCA1 mutation carriers with a false discovery rate-adjusted p value of 0.029 for overall association of the haplotype." (PMID 27796716, 2017). "In about 5–10%, breast cancer occurs in a hereditary setting, most commonly due to BRCA1 or BRCA2 germline mutations, which lead to a 40–80% lifetime risk of developing breast cancer as well as a 30–40% lifetime risk of ovarian cancer development." (PMID 28569220, 2017). "Confirmed deletions overlapping a total of nine gene loci were found associated with breast cancer risk, and a total of 13 gene loci associated with ovarian cancer risk in BRCA1 pathogenic variant carriers." (PMID 28145423, 2017). "A genetic testing for a specific pathogenic BRCA1 variant (c.5074+2T>C) was performed on one breast cancer patient (mother)." (PMID 28717669, 2017). "According to a large nationwide prospective Korean Hereditary Breast Cancer (KOHBRA) study, 153 distinct BRCA1/2 mutations have been identified in Korean breast cancer patients with a family history of breast/ovarian cancer resulting in a prevalence of 22.3%." (PMID 28351343, 2017). "Despite large sample sizes, these studies generally lacked detailed information on potentially important covariates including BRCA1/2 mutation carrier status, breast cancer family history, and treatment for first breast cancer." (PMID 28724391, 2017). "Cisplatin-based chemotherapy was seemed to be effective in a high proportion of patients with BRCA1 mutation breast cancers." (PMID 29108309, 2017). "Carriers of BRCA1 pathogenic variants are at increased risk for developing breast cancer and/or ovarian cancer, but the precise level of these risks is uncertain." (PMID 28145423, 2017). "BRCA1 mutations are one of the most established risk factors for breast cancer, resulting in loss of BRCA1 protein function, reduced expression or disturbed subcellular distribution of the protein." (PMID 28863181, 2017). "Our data confirm that synthetic lethality can be induced in BRCA1-deficient breast cancer cells through depletion of RAD52, possibly through the accumulation of a toxic fork repair intermediate." (PMID 29145865, 2017). "BRCA1 is a human tumor suppressor gene that produces the breast cancer type 1 susceptibility protein." (PMID 28157161, 2017). "Yet, the speed and low price of current BRCA1 mutation screening make it a more popular method to assess BRCA1 status in breast cancer than measuring the actual expression and subcellular distribution of BRCA1 in histological specimens." (PMID 28863181, 2017).
breast cancer (continued). "We comprehensively screened 68 breast/ovarian cancer families for small-range mutations, 221 families for LGRs, and 1,022 unselected breast cancer cases for Colombian founder mutations in BRCA1/2." (PMID 28680148, 2017). "With regard to breast cancer, BRCA1/2 mutations are reported to be mainly responsible for the development of hereditary breast cancer, and corresponding gene screening has become a routine tool for decreasing the risk ratio of mammary malignancies." (PMID 29109519, 2017). "A prime example of this was the demonstration that breast cancer 1 susceptibility gene (Brca1)-deficient breast cancers originated from luminal progenitors, contrary to the expectation that these were of basal stem cell origin." (PMID 28381598, 2017). "We have shown that splicing reporter minigenes of the breast cancer genes BRCA1 and BRCA2 are useful tools to functionally test DNA variants." (PMID 28339459, 2017). "This study is the first to report on methylation of male breast cancers arising in BRCA1 mutation carriers." (PMID 28893223, 2017). "The estimated cumulative risk of breast cancer by age 70 years for BRCA1 mutations carriers was 14% (95% CI 5–38) compared to 3% for the general Colombian population (relative risk of breast cancer 4.05)." (PMID 28680148, 2017). "For example, mutations in the RAD54 homolog RAD54B and in CtIP are associated with lymphomas and colon cancer, whereas BRCA1 is frequently associated with breast cancer." (PMID 28471392, 2017). "In conclusion the present study demonstrates the great importance of properly assessing breast cancer HER2 status when determining the likelihood of a BRCA1/2 mutation." (PMID 27796713, 2017). "The BRCA-1 gene encodes a tumor suppressor protein involved in the repair of DNA damage, and its downregulation is associated with sporadic breast cancers." (PMID 29104258, 2017). "Both the estimated relative risk of breast cancer by age 70 years (4.05) and the corresponding cumulative risk for BRCA1 mutation carriers (14%) were lower than expected." (PMID 28680148, 2017). "One study examined breast cancer incidence in BRCA1 mutation carriers who had undergone oophorectomy to prevent onset of ovarian cancer." (PMID 28865460, 2017). "All these evidences have led to the design of phase III Olympia trials which are currently investigating the activity of olaparib as single agent both in metastatic and adjuvant treatment of breast cancer patients with germ-line BRCA1-2 mutations." (PMID 28055979, 2017). "We comprehensively screened 68 Colombian breast/ovarian cancer families for small-range mutations, 221 families for large-genomic rearrangements, and 1,022 unselected breast cancer cases for Colombian founder mutations in BRCA1/2." (PMID 28680148, 2017). "Using mouse genetic models, we further show that attenuation of Pol II pausing reduces incidence of Brca1-associated mouse mammary tumour incidence in a DNA repair-independent manner." (PMID 28649985, 2017). "For example, the GEMM‐ESC strategy was used to introduce the Met proto‐oncogene in a GEMM of BRCA1‐associated breast cancer, which yielded a novel mouse model of BRCA1‐deficient metaplastic breast cancer." (PMID 28028012, 2017). "We investigated the prevalence of BRCA1/2 small mutations and large genomic rearrangements in high risk breast cancer patients who attended a genetic counseling clinic." (PMID 28205045, 2017). "In the TCGA breast cancer data, 13 and 14 samples contain at least one somatic mutation in BRCA1 and BRCA2, respectively." (PMID 29146938, 2017). "Genetic testing for breast cancer 1 (BRCA1) and breast cancer 2 (BRCA2) gene mutations can identify women at increased risk for breast and ovarian cancer." (PMID 28880857, 2017). "In an attempt to identify new breast cancer susceptibility loci, a genome-wide linkage analysis was conducted in 96 non-BRCA1/2 families with breast or breast-ovarian cancer." (PMID 29262523, 2017).